CHKB (choline kinase beta)
Description:
Has a key role in phospholipid metabolism, and catalyzes the first step of phosphatidylethanolamine and phosphatidylcholine biosynthesis.
Synonyms: CK; CKB; EK; EKB; CKEKB; CHETK; CHKL; MDCMC
Tractability: Small molecule: a structure with a bound ligand is known; it has a high-quality binding pocket. PROTAC: ubiquitination databases record sites on it; its protein half-life has been measured; a small molecule that binds it is known.
Target class: Enzyme; Transferase
Gene: Protein-coding gene on chromosome 22 (50,578,959 to 50,601,455, reverse strand). Ensembl gene ENSG00000100288.
Subcellular location (Human Protein Atlas): Cytosol
Pathways (Reactome):
Metabolism: Synthesis of PC; Synthesis of PE
Gene Ontology:
Molecular function: choline kinase activity; ethanolamine kinase activity
Biological process: phosphatidylethanolamine biosynthetic process; CDP-choline pathway
Cellular component: cytoplasm; cytosol
Genetic constraint (gnomAD): Loss-of-function variants: 46 observed, 57.96 expected, observed/expected ratio (o/e) 0.79, 90% interval 0.63 to 1.01. The upper end of that interval is the gene's LOEUF score, 1.01, which puts it in group 4 of 6, group 1 being the genes least tolerant of losing a copy. Missense variants: 517 observed, 507.95 expected, observed/expected ratio (o/e) 1.02, 90% interval 0.95 to 1.1. Synonymous variants: 224 observed, 198.9 expected, observed/expected ratio (o/e) 1.13, 90% interval 1.01 to 1.26.
Homologues: Orthologues: chimpanzee CHKB (99% identical), macaque CHKB (93% identical), pig CHKB (91% identical), guinea pig CHKB (89% identical), dog CHKB (87% identical), mouse Chkb (86% identical), rat Chkb (85% identical), rabbit CHKB (67% identical), tropical clawed frog chkb (57% identical), zebrafish chkb (57% identical), Caenorhabditis elegans cka-2 (39% identical), Caenorhabditis elegans cka-1 (38% identical), and 5 more. Paralogues in human: CHKA (56% identical), ETNK1 (28% identical), ETNK2 (28% identical).
Diseases named in the same sentence as CHKB in open-access papers:
CHKB is named in the same sentence as 45 diseases in open-access papers, as found by Europe PMC text mining. Sharing a sentence is not in itself a finding about the gene and the disease. The quoted sentences say what the papers report.
muscular dystrophy (14 papers, 2019 to 2026). Muscular dystrophy (MD) refers to a group of more than 30 genetic diseases characterized by progressive weakness and degeneration of the skeletal muscles that control movement. "Loss-of-function variants of the CHKB gene cause an autosomal recessive disease described as an early onset congenital megaconial (large peripheral mitochondria) muscular dystrophy." (PMID 42292914, 2026). "CHKB deficiency disrupts mitochondrial function and is linked to muscular dystrophy, while PC supplementation restores membrane integrity in neurodegenerative contexts." (PMID 40417780, 2025). "In contrast to CHKA disease-causing variants, autosomal recessive variants in CHKB cause a neuromuscular disorder characterized by muscular dystrophy with intellectual disability and cardiomyopathy (OMIM #602541)." (PMID 41308990, 2025). "They demonstrated the differential diagnosis of patients with heart failure, muscular dystrophy, and intellectual disability carrying CHKB variants." (PMID 39465137, 2024). "In mice, loss of CHKB function results in a muscular dystrophy that present a rostrocaudal gradient with proximal muscle most affected." (PMID 38749543, 2024). "A thought-provoking form of muscular dystrophy is because of autosomal recessive loss of function of the CHKB gene (#602541; OMIM)." (PMID 38749543, 2024). "Congenital muscular dystrophies associated with CHKB loss-of-function mutations display distinct enlarged (megaconial) mitochondria in the peripheries of muscle fiber and absence of mitochondria in the centers." (PMID 35322809, 2022). "In humans and mice, inactivation of the CHKB gene (Chkb in mice) causes a recessive rostral-to-caudal muscular dystrophy." (PMID 35322809, 2022). "Mitochondrial abnormalities have been described in other muscle diseases such as collagen VI-related myopathies, muscular dystrophy due to choline kinase beta (CHKB) gene mutations, myositis, and Duchenne muscular dystrophy." (PMID 33308300, 2020). "In humans, mutations in CHKB cause phosphatidylcholine deficiency in myofibers and muscular dystrophy." (PMID 32399287, 2020). "The previous observation that AAV-mediated expression of human CHKA in Chkb−/− mice ameliorated the muscular dystrophy phenotype suggests that increased CHKA expression could compensate for loss of CHKB function." (PMID 41308990, 2025). "While loss-of-function mutations in human CHKB are associated with muscular dystrophy, the impact of its ectopic expression is currently unknown." (PMID 38580899, 2024). "Notably, both DMD and CHKB are associated with conditions involving muscular dystrophy and autism." (PMID 39103847, 2024). "Here, we assessed the therapeutic potential of an AAV therapy for the treatment of CHKB-mediated muscular dystrophy." (PMID 42292914, 2026). "Among other muscular dystrophies, 20 of 24 patients (83.3%) had variants in LAMA2 (n = 6), LMNA (n = 5), COL6A1 (n = 4), CHKB (n = 2), COL6A2 (n = 2), and COL6A3 (n = 1)." (PMID 40494860, 2025). "CHKB-mediated muscular dystrophy is the only defect in the synthesis of a major membrane lipid known to cause a muscular dystrophy." (PMID 38749543, 2024). "Loss of plasma membrane integrity in affected muscle is a hallmark of muscular dystrophies, and consistent with this an increase in creatine kinase level is observed in plasma of CHKB patients and Chkb−/− mice." (PMID 38749543, 2024). "Muscular dystrophy, congenital, megaconial type (OMIM 602541) is an autosomal recessive dystrophy caused by loss of function of CHKB gene and is the only defect in phospholipid synthesis that can cause a muscular dystrophy." (PMID 35322809, 2022). "Mutations in the CHKB gene can result in significantly reduced or absent choline kinase beta activity, leading to congenital muscular dystrophies such as MCMD." (PMID 39465137, 2024).
muscular dystrophy (continued). "Furthermore, individuals with CHKB-related muscular dystrophy frequently exhibit conditions such as ASD or ADHD, reinforcing the link between CHKB mutations and a spectrum of neurological disorders." (PMID 39103847, 2024). "It is unclear how a defect in a gene required for the synthesis of a major phospholipid in mammalian cells causes a muscular dystrophy, especially given that global inactivation of the CHKB/Chkb gene (human or mouse) does not affect the level of the product of its biochemical pathway, PC." (PMID 35322809, 2022). "Our study has determined how lipid metabolism is specifically altered in affect Chkb−/− affected muscle, how to reverse these metabolic alterations, and determined a potential treatment for CHKB mediated muscular dystrophy." (PMID 35322809, 2022).
narcolepsy (6 papers, 2009 to 2024). A sleep disorder characterized by a tendency for excessive sleepiness during the day which occurs even after adequate sleep in the nighttime. "As a result, an SNP located between CPT1B and CHKB on Chromosome 22 was found to be associated with narcolepsy." (PMID 24705288, 2014). "The new narcolepsy-susceptibility region, CPT1B/CHKB, was discovered through a GWAS performed to search for genetic factors other than the established factor, HLA." (PMID 24705288, 2014). "CPT1B, CHKB and HLA are candidates for susceptibility to CNS hypersomnias (EHS), as well as narcolepsy with cataplexy." (PMID 19404393, 2009). "SNP rs5770917 located between CPT1B and CHKB, and HLA-DRB1*1501-DQB1*0602 haplotype were previously identified as susceptibility loci for narcolepsy with cataplexy." (PMID 19404393, 2009). "Thus, either of these two genes (CPT1B and CHKB) is a plausible candidate for susceptibility to CNS hypersomnias (EHS), as well as narcolepsy with cataplexy." (PMID 19404393, 2009). "In cohort studies in Japan and South Korea, GWAS was used to identify a non-HLA-related variant located between CHKB and CPT1B that is significantly associated with narcolepsy." (PMID 38725645, 2024).
congenital muscular dystrophy (3 papers, 2021 to 2022). A muscular dystrophy that is characterized by diminished muscle tone (hypotonia), progressive muscle weakness and degeneration (atrophy), abnormally fixed joints, spinal rigidity, and delays in reaching motor milestones such as sitting or standing unassisted. "Homozygous loss-of-function variants in human CHKB are associated with a congenital muscular dystrophy." (PMID 35151687, 2022). "Autosomal recessive CHKB mutations cause a rare form of congenital muscular dystrophy known as megaconial congenital muscular dystrophy (MCMD)." (PMID 36175989, 2022). "Megaconial Congenital Muscular Dystrophy (CMD) is a rare autosomal recessive disorder characterized by enlarged mitochondria located mainly at the periphery of muscle fibers and caused by mutations in the Choline Kinase Beta (CHKB) gene." (PMID 34518586, 2021).
autism (2 papers, 2022 to 2024). Persistent deficits in social interaction and communication and interaction as well as a markedly restricted repertoire of activity and interest as well as repetitive patterns of behavior.
breast carcinoma (2 papers, 2014 to 2021). "Both CHKB and KLHDC7B are located on chromosome 22q13.33, where KLHDC7B is involved in breast cancer and lymph node metastasis in cervical cancer and CHKB encodes choline kinase (ChoK) beta." (PMID 25106096, 2014).
cardiomyopathy (2 papers, 2022 to 2024). A disease of the heart muscle or myocardium proper. "Nevertheless, mitochondrial encephalomyopathy, intellectual disability, infantile hypotonia, and cardiomyopathy in patients affected by a mutation in gene CHKB are associated." (PMID 35199317, 2022). "Thus, nonsense variants of CHKB are more likely to induce cardiomyopathy, which is the primary cause of early death in affected individuals." (PMID 39465137, 2024).
Adrenocortical carcinoma (1 paper, 2022). "CHKB and PEMT occupy the highest mutation frequencies in Adrenocortical carcinoma (ACC)." (PMID 36451813, 2022).
cardiac conduction disorder (1 paper, 2024). "The patient exhibited severe heart dysfunction and a complex cardiac conduction disorder due to a complete loss of function of CHKB caused by a homozygous nonsense variant." (PMID 39465137, 2024).
Cataplexy (1 paper, 2009). A sudden and transient episode of bilateral loss of muscle tone, often triggered by emotions. "Thus, SNP rs5770917 located between CPT1B and CHKB might be involved in the pathogenesis of excessive daytime sleepiness, not cataplexy." (PMID 19404393, 2009).
developmental delay (1 paper, 2021). "Pathogenic variants in the CHKB gene, encoding choline kinase beta, an enzyme involved in the synthesis of phosphatidylcholine, cause megaconial congenital muscular dystrophy in humans (associated with developmental delay and autistic behavior) and to rostrocaudal muscular dystrophy in mouse." (PMID 34360941, 2021).
dilated cardiomyopathy (1 paper, 2024). Cardiomyopathy which is characterized by dilation and contractile dysfunction of the left and right ventricles. "We report a rare case presenting with dilated cardiomyopathy (DCM) as the dominant feature with a homozygous nonsense variant of CHKB (c.598delC, p.Q200Rfs*11)." (PMID 39465137, 2024). "Herein, we report a rare case presenting with dilated cardiomyopathy as the dominant feature with a homozygous nonsense variant of CHKB, and the related therapeutic strategy." (PMID 39465137, 2024).
glioma (1 paper, 2022). A benign or malignant brain and spinal cord tumor that arises from glial cells (astrocytes, oligodendrocytes, ependymal cells). "The relationship between CHKB and glioma haven’t been explored." (PMID 35558067, 2022).
melanoma (1 paper, 2021). A malignant, usually aggressive tumor composed of atypical, neoplastic melanocytes. "Interestingly, gene amplification of CHKB is only detected in pancreatic cancer and melanoma, while gene deletion of CHKB is documented in ovary, uterine and several other solid tumors." (PMID 34202989, 2021).
microcephaly (1 paper, 2023). A congenital or acquired developmental disorder in which the circumference of the head is smaller than normal for the person's age and sex. "Recent studies have shown that CHKB deficiency leads to congenital myotonic dystrophy, including microcephaly and facial dysmorphism." (PMID 36572794, 2023).
muscle disorders (1 paper, 2024).
Obesity (1 paper, 2020). Accumulation of substantial excess body fat. "We detected significant GxE interaction between CHKB-rs75187587 (MAF = 0.05) and SSB intake on obesity." (PMID 32399287, 2020).
Skin Cutaneous Melanoma (1 paper, 2022). "Furthermore, the SNV percentage heatmap showed that at the pan-cancer level, CHKB had the highest mutation frequency in Uterine Corpus Endometrial Carcinoma (UCEC) and Skin Cutaneous Melanoma (SKCM), while PEMT had the highest mutation frequency in UCEC." (PMID 36451813, 2022).
cancer (5 papers, 2021 to 2023). A tumor composed of atypical neoplastic, often pleomorphic cells that invade other tissues. "In addition, CHPT1, AHCYL1, and CHKB have been demonstrated to be associated with roles that lead to other cancers and affect patient outcomes, although relevant studies are scarce in BC." (PMID 38239641, 2023). "It is conceivable that CHKB deletion would result in an altered balance of the α versus β isoforms and an increased ratio of CHKα in cancer cells." (PMID 34202989, 2021). "The waterfall plots further visualized the mutation types of CHKB and PEMT in pan-cancer." (PMID 36451813, 2022). "To obtain information on genetic alterations of choline kinase in human cancers, we searched the Cancer Genome Atlas (TCGA) for the presence and frequency of gene amplification, deletion and mutation on CHKA and CHKB in various human lymphoid malignancies as compared to solid tumors." (PMID 34202989, 2021). "Therefore, the upregulation of CHK activity in cancer probably results from an increase in CHKA expression, which would lead to a higher proportion of CHKA-]–CHKA dimers exerting a higher CHK activity level than CHKA–CHKB heterodimers or CHKB–CHKB homodimers." (PMID 35740569, 2022).
tumor (2 papers, 2021 to 2023). "Consequently, the aberrant expression of CHKB may influence the growth and metabolism of tumor cells." (PMID 38103068, 2023).
myopathies (1 paper, 2021). "However, the CHKB RNA levels are still considerable in SkM and heart (TPM, 18 and 28), which is consistent with CHKB being linked to myopathies." (PMID 35076500, 2021).
CHKB also shares sentences with these, for which no sentence is quoted: Intellectual disability (2 papers); acute lymphoblastic leukemia (1); autism spectrum disorder (1); cervical cancer (1); chronic kidney disease (1); colon cancer (1); congenital myopathies (1); Duchenne muscular dystrophy (1); epilepsy (1); gastric cancer (1); heart failure (1); ichthyosis (1); liver cancer (1); lymph node metastasis (1); megaconial type congenital muscular dystrophy (1); mitochondrial encephalomyopathy (1); myositis (1); nasopharyngeal carcinoma (1); neurodevelopmental disorder (1); neurogenetic diseases (1); neurological disorders (1); pancreatic cancer (1); skin changes (1); uterine corpus endometrial carcinoma (1); Walker-Warburg syndrome (1).